DNMT1 (DNA methyltransferase 1)
Diseases named in the same sentence as DNMT1 in open-access papers (continued):
Sharing a sentence is not in itself a finding about the gene and the disease.
cancer (continued). "NNMT‐DNMT1 axis plays an essential role in maintaining cancer cell sensitivity to OXPHOS inhibition, and the statuses of NNMT and DNMT1 genes are faithful biomarkers for OXPHOS‐targeting cancer therapies." (PMID 36382559, 2022). "In our research, BCAT1 expression was correlated with the three DNA methyltransferase genes––DNMT1, DNMT3A, and DNMT3B in some cancers." (PMID 34984849, 2022). "In this review, we mainly summarize the roles of DNMT1, DNMT3A, and DNMT3B in cancer, hoping to shed new light on the treatment of cancer." (PMID 36091786, 2022). "Significant correlations of BCAT1 expression with the three methyltransferases—DNMT1, DNMT3A, and DNMT3B—were detected in some cancers." (PMID 34984849, 2022). "In order to study the role of DNMT1 in the prognosis of LABC patients, a total of 100 breast pretreatment tumor tissues were assessed for the expression of the DNMT1 protein in cancer cells and their adjacent stromal fibroblasts." (PMID 35719957, 2022). "DNA methylation is an important epigenetic mechanism regulating gene expressions through three DNA methyltransferases (DNMT1, DNMT3A, and DNMT3B) and affects cancer cell behaviors." (PMID 33612479, 2021). "DNMT1 is responsible for maintaining global methylation and aberrant CGI methylation in human cancer cells, whereas DNMT3a and DNMT3b are believed to act as maintenance and de novo methyltransferases." (PMID 33959155, 2021). "In epithelial cancers, LMP1 indeed mediates the expression of host genes via DNA methylation through up-regulation of DNMT1, DNMT3A and DNMT3B, which further promotes the migration of cancer cells." (PMID 34946098, 2021). "In agreement with the outcomes from cancer therapies, a few studies showed that downregulation of TET1 expression or upregulation of DNMT1 by air pollutants is observed, resulting in DNA hypermethylation and TSG silencing." (PMID 34203568, 2021). "Aberrant DNA methylation has been established as key molecular events contributing to tumorigenesis, and targeting DNMT1, DNMT3A, and DNMT3B with 5-azacytidine (Aza) and 5-Aza-2’-deoxycytidine were suggested as promising strategies for cancer treatment." (PMID 33589600, 2021). "Thymoquinone also downregulates the expressions of containing plant homeodomain (PHD) and really interesting new gene (RING) finger domains 1 DNMT1,3A,3B, (UHRF1), HDAC1,4,9, G9A, KMT2A,B,C,D,E, and KDM1B genes in Jurkat cells and MDA‐MB‐468 cancer cell lines." (PMID 33747489, 2021). "The miR-148b and miR-320a target DNA methyltransferase 1 (DNMT1) and hypoxia inducible factor 1 subunit alpha (HIF1α), respectively, which have the potential of promoting cancer cell metastasis and angiogenesis." (PMID 34852849, 2021). "Among epigenetic genes, DNA methylation related epigenetic modifiers, DNMT1, DNMT3A, MBD1, MBD4, TET1, TET2, and TET3, have been studied related to cancer." (PMID 32093698, 2020). "Evidently, NFE2L2 expression is closely related to the expression of DNMT1, DNMT2, DNMT3A, and DNMT3B across human cancers, especially in COAD, KIRP, LGG, and UVM." (PMID 33101586, 2020). "In our study, we also found that NFE2L2 expression was closely correlated with that of 4 DNA methyltransferases (DNMT1, DNMT2, DNMT3A, and DNMT3B) in human cancers, especially in COAD, KIRP, LGG, and UVM." (PMID 33101586, 2020). "So far we have demonstrated that 2i has a broad effect on UHRF1 and DNMT1 expression in cancer cells and that the effect of 2i on UHRF1 and DNMT1 expression is due to specific inhibition of MEK/ERK pathway." (PMID 30696879, 2019). "For global DNA hypomethylation, a diminished interaction was suggested between UHRF1 and DNMT1, although UHRF1 expression is enhanced in all cancers so far investigated." (PMID 30669400, 2019). "A significant decrease was also found in the expression levels of crucial epigenetic players UHRF1, DNMT1, and HDAC7, known to inhibit the expression of several tumor suppressor genes in cancer (LogFC<−1.7; p < 0.001)." (PMID 31482051, 2019).
cancer (continued). "Due to stronger effect of EZH2 knockdown on neuronal differentiation in different cancer cells, we subsequently focused on the role of EZH2 in the regulation of expression of HDAC1, LSD1, or DNMT1, and of β-CAT and SMAD transducers as well." (PMID 31130994, 2019). "Earlier studies showed that knockdown of DNMT1 or double knockdown of DNMT1 and DNMT3B induces DNA demethylation in various cancer cells." (PMID 31064417, 2019). "EZH2, LSD1, DNMT1, and HDAC1 are co-expressed in many types of cancer cells, as well as in neural progenitor/stem cells." (PMID 31130994, 2019). "Given the profound effect of 2i culture condition on mESCs pluripotency, DNA methylation and UHRF1/DNMT1 expression, here we investigated if and how 2i regulates UHRF1/DNMT1 expression in cancer cells." (PMID 30696879, 2019). "After scanning our oral cell lines, we observed that the mRNA expression of DNMT1 and DNMT3B was higher in most cancer cell lines compared with normal cell lines." (PMID 31624299, 2019). "Here, we show that EZH2, LSD1, DNMT1, and HDAC1 form interactions themselves, meanwhile, they also interact with SMAD proteins and β-CATENIN in cancer cells." (PMID 31130994, 2019). "Genetic or pharmacological DNMT1 inhibition has been reported to be sufficient to lead to TSG re-expression and cell growth arrest in a variety of cancer cells in vitro, such as lung, esophagus, stomach, breast, cervix, brain, head, and neck cancer cells." (PMID 31060628, 2019). "Single knockdown of HDAC1, HDAC2, HDAC3, LSD1, DNMT1, and EZH2 generated different effects of neuron-like differentiation in cell lines of different cancer types." (PMID 31130994, 2019). "In fact, by three different approaches, the co-expression score of UHRF1 and DNMT1 is higher than that of DNMT1 and DNMT3A, which was previously proposed to be coordinately co-expressed in order to maintain DNA methylation homeostasis in cancer cells." (PMID 30696879, 2019). "Only DNA methyltransferase (DNMT) genes were presented in results: DNMT1, DNMT3A, and DNMT3B were all highly expressed in 8, 6, and 9 cancer samples compared with normal, respectively." (PMID 31828117, 2019). "Knocking down DNMT1 noticeably inhibits cell viability in PDAC and induces apoptosis, making it an excellent target for anti-cancer therapy." (PMID 29927979, 2018). "Conversely, DNMT1 was required for H3 deacetylation and di- and trimethylation of H3K9 in cancer cells." (PMID 29449903, 2018). "CTA genes have been shown previously to lose methylation and become derepressed in several cancer cell types after treatment with the methyltransferase inhibitor 5′aza-2-deoxycytidine (Aza) and in the HCT116 DNMT1 mutant line using locus-specific approaches." (PMID 29598829, 2018). "And as the key downstream effectors of OPN for cancer stemness, the expression levels of BMI1 and HIF1α were increased when DNMT1 was up-regulated in CD133+/CD44+ cells with shOPN." (PMID 30064482, 2018). "Another interesting chemokine ligand is CXCL14, which we observed to be hypermethylated and underexpressed in two cancer types (breast and colon), but which exhibited a distinctive anti-correlative expression pattern with EZH2/DNMT1 in most cancer types." (PMID 27899617, 2017). "Down-regulation of TIP60 has been reported in many cancers and TIP60 has a well-established role in regulation of DNMT1." (PMID 29268763, 2017).
cancer (continued). "Up-regulating DNMT1 and driving malignant phenotypes by epigenetic mechanism play a crucial role in NPC, especially in the early stage of this cancer." (PMID 29872698, 2017). "We also tested the effect of β-elemene in NPC tumor growth and DNMT1, EZH2 expression in nude mouse xenografted cancer model." (PMID 28360411, 2017). "In contrast, for those exhibiting consistent hypomethylation/overexpression in cancer, their expression across tumors is more likely to be consistently positively correlated with EZH2 or DNMT1 (or both)." (PMID 27899617, 2017). "Since they showed in vitro activity over DNMT1, inhibition of HCT116 cell proliferation and weak global DNA demethylation in cancer cells, they represent lead molecules to be further optimized." (PMID 28067760, 2017). "Several lines of evidence demonstrated that high expression of DNMT1 existed in several cancer types including NPC and that targeting DNMT1 suppressed cancer cell growth." (PMID 28360411, 2017). "Involved in tumourigenesis and cancer progression, UHRF1 is suspected of being a hepatocellular oncogene due to its overexpression having the ability to destabilize and delocalize DNMT1." (PMID 28587163, 2017). "Inhibition of DNMT1 restores expression of tumor suppression-related genes such as p16 and RGS10 and contributes to reduced cancer cell viability, decreased invasive capability, and enhanced treatment sensitivity." (PMID 27087738, 2016). "We therefore explored the expression status of DNMT1 and DNMTB versusRASSF1A expression in various cancers utilizing data from The Cancer Genome Atlas (TGCA)." (PMID 27294960, 2016). "Consistent with previous publications, these RNA-seq data indicate that both DNMT1 and DNMT3A are also frequently overexpressed in these cancers." (PMID 27462454, 2016). "Together, these data suggest that disruption of the pRb-DNMT1 pathway leads to a decrease in MEG3 expression, thereby contributing to the pro-proliferative state of certain cancer cells." (PMID 27832204, 2016). "Moreover, the mechanistically interaction between EZH2 and DNMT1 regulated their downstream targets, thereby controlling DNA methylation and/or transcriptional repressed micoRNAs (miRNAs) expression, which contributed to growth and progression in several cancer types." (PMID 27421653, 2016). "As an interesting perspective in the field of cancer therapy, we have recently identified an inhibitor of UHRF1 (a uracil derivative) that targets the SRA domain with subsequent impact on DNMT1/UHRF1 interactions and decrease in global DNA methylation." (PMID 27839516, 2016). "As critical epigenetic and oncogenetic factors, increased expressions of DNMT1 and EZH2 have been shown in several cancer types including lung through silencing tumor suppressor genes via hypermethylation and other mechanisms." (PMID 27421653, 2016). "Thus, targeting DNMT1 could be a potential in the prevention and treatment of cancers." (PMID 27421653, 2016). "The Snail-G9a-DNMT1 protein complex has been shown not only to decrease E-cadherin levels but also FBP1, increasing glucose uptake, inducing glycolysis and cancer stem cell like characteristics." (PMID 25878567, 2015). "DNA (cytosine-5-)-methyltransferase 1 (DNMT1) is overexpressed in many cancers and is correlated to the aberrant methylation in human cancer cells." (PMID 26292924, 2015). "DNMT1 and RASSF1A gene high expression in cancer patients, perhaps, can be used as a tumor marker for the early diagnosis of tumors." (PMID 25886188, 2015). "The epigenetic gene silencing effect of gene promoter region mediated through the CpG methylation by DNA methyltransferase 1 (DNMT1) and other members of the DNMT family have key roles in the inhibition of tumor-suppressor gene expression in cancer cells." (PMID 26631279, 2015). "The effect of vIL-6 on DNMT1 described here,enriched our knowledge about the role of KSHV in epigenetic modification in cancer." (PMID 24675762, 2014).
cancer (continued). "In this context, recently we found that the epigallocatechin-3-gallate (EGCG), a natural anti-cancer drug induces G1 cell arrest and apoptosis in Jurkat cells by down-regulating UHRF1 and DNMT1 expression, with subsequent up-regulation of p16INK4A gene." (PMID 23688286, 2013). "Consistent with DNMT1 being a suppressor of abnormal DDR activation, deletion of DNMT1 in cancer cells was found to result in cell cycle arrest in G2/M and mitotic catastrophy in escapes." (PMID 24065984, 2013). "DNA methyltransferase 1 (DNMT1) is the enzyme most responsible for epigenetic modification of human DNA and the intended target of approved cancer drugs such as 5-aza-cytidine and 5-aza-2′-deoxycytidine." (PMID 24236046, 2013). "At that time, several mRNA targets of miR-148a such as DNA methyltransferase 3 beta (DNMT3B), DNA methyltransferase 1 (DNMT1), BCL2 were described in various cancers using transient transfection and Western blot analysis." (PMID 23383211, 2013). "Previous studies on cancers reported that miR-152 can bind to the 3′ untranslated region (UTR) of DNMT1." (PMID 22295098, 2012). "Moreover, overexpression of DNMT1, DNMT3A, and DNMT3B at the mRNA level was observed in bladder, kidney, colon, and pancreas human cancers." (PMID 41226543, 2025). "Conversely, Conversely, in BRCA-mutant cancers, DNMT1 promotes resistance to PARP inhibitors (PARPi) by modulating DNA repair processes such as RPA complex recruitment and replication fork stability; thus, DNMT1 inhibition sensitizes tumors to PARPi." (PMID 41381440, 2025). "G9a and UHRF1 were significantly overexpressed in cancer compared to normal ducts (p < 0.001 for both), although DNMT1 was not significantly overexpressed in this comparison." (PMID 39810240, 2025). "A recent study demonstrated that the induction of DNA damage by DNMTi, in the presence of DNMT1, without the re-expression of tumour suppressors, was responsible for the anti-cancer effects of DNMTi." (PMID 40011240, 2025). "Furthermore, investigations have indicated that utilizing the DNMT inhibitor decitabine in conjunction with doxorubicin effectively reduced DNMT1 activity, DNA methylation, and cancer cell proliferation." (PMID 40006021, 2025). "DNMT1 is a critical enzyme responsible for maintaining DNA methylation patterns and regulating gene expression, particularly in tumor suppressor genes (TSGs) such as p16INK4 and BRCA1, frequently silenced in cancer." (PMID 39996888, 2025). "In contrast, silencing NUSAP1 markedly decreases the expression of DNMT1 at both mRNA and protein levels, indicating that NUSAP1 may affect the malignant behavior of cancer cells through modulation of DNMT1 expression." (PMID 40535133, 2025). "One of the most studied is RG108, a small molecule that directly binds the catalytic pocket of DNMT1, leading to reversible, non-cytotoxic demethylation in various preclinical cancer and inflammatory models." (PMID 41335282, 2025). "Furthermore, the interaction between DNMT1 and other signaling pathways, such as the PI3K‐AKT pathway, highlights its complex role in cancer biology." (PMID 40387566, 2025). "Overexpression of DNMT1 or recruitment of DNMTs by proteins such as UHRF1/2 can exacerbate hypermethylation-mediated silencing of genes that regulate cell cycle, apoptosis, and DNA repair, all of which are hallmarks of cancer." (PMID 40558829, 2025). "Also, TQ has demonstrated a cytotoxic effect in vitro on leukemic cells by inhibiting DNMT1 and HDAC1, representing a potential epigenetic treatment against cancer." (PMID 39769174, 2024).
cancer (continued). "A significant positive correlation between G9a and DNMT1 expression was also found in NSCLC cell lines, when the evaluation was carried out with data from the cancer cell line encyclopedia (CCLE) database or when qPCR was used in the cells available in our laboratory." (PMID 39488528, 2024). "Thus, one of the studies focused on investigating the inhibitory effect on the epigenetic code of cancer cells, which is controlled by the UHRF1/DNMT1/HDAC1 complex." (PMID 39769174, 2024). "Overexpression of DNMTs (e.g., DNMT1, DNMT3A and DNMT3B) could promote DNA hypermethylation, which was closely related to the prognosis in cancer patients (Weisenberger, Lakshminarasimhan & Liang, 2022)." (PMID 38766487, 2024). "Notably, DNMT1, NSUN2, and TET2 showed consistent positive correlations with WDHD1 expression across all types of cancers." (PMID 37759234, 2023). "Interestingly, in the context of its epigenetic role, studies have confirmed that CHD4 can interact with the methylation enzymes DNMT1, DNMT3B, EZH2 and G9a in cancer progression." (PMID 36681835, 2023). "Overexpression of LinC00472 can recruit DNMT1, DNMT3A and DNMT3B to mediate the methylation of oncogenic factor MCM6, which leads to the down-regulation of its expression level, and then inhibits cancer progression by inactivating MEK/ERK signaling pathway." (PMID 37901333, 2023). "However, the expression of PAS1 is regulated by DNMT1 and leads to the decrease of the expression level, which undermines the inhibition effect of PAS1 on PH20 and leads to the progression of cancer." (PMID 37901333, 2023). "By contrast, expression of EZH2 in cancer cells may dampen anti-tumor immunity and hinder the infiltration of the tumor by effector T cells through EZH2- and DNMT1-mediated epigenetic silencing of TH1-type chemokines (i.e., CXCL9 and CXCL10)." (PMID 36627707, 2023). "Although DNMT1 was considered to be highly expressed in cancer cells, the increase in expression of de novo methyltransferases, DNMT3, also have been proven to be involved with cancer cells." (PMID 36903908, 2023). "Similarly, Disulfiram, RG108, and the quinolone-based molecule SGI-1027 have been shown to have antitumor activities by inhibiting DNMT1 and inducing a genome-wide demethylation and TSG reactivation in cancer cells." (PMID 36060265, 2022). "NNMT overexpression and DNMT1 downregulation exhibit additive effects on reducing cancer cell sensitivity to OXPHOS inhibition, suggesting these proteins function together in maintaining a cancer cell state, which is sensitive to OXPHOS inhibition." (PMID 36382559, 2022). "In addition, OAS3 was positively correlated with four major DNA methyltransferases including DNMT1, DNMT2, DNMT3A, and DNMT3B in most cancer types." (PMID 35592250, 2022). "Therefore, it would be interesting to examine the effects of DNMT1 and DNMT3 A on EMT, cancer growth, and anti-cancer drug resistance." (PMID 35682560, 2022). "Recently, DNMT1 is shown to promote malignant events of cancers through the epigenetic and non-epigenetic processes." (PMID 35838271, 2022). "This is likely because DNMT1 is not a de novo DNA methyl transferase and it cannot generate a DNA methyl pattern critical for cancer cell dependency of OXPHOS by itself." (PMID 36382559, 2022). "Expression of NNMT remains low in tumor xenografts driven by OXPHOS inhibition‐sensitive cancer cell lines (NCI‐H82 and MDA‐MB‐453) compared with those driven by the resistant cancer cells (CFPAC‐1 and NCI‐H82‐OE‐NNMT/sh‐DNMT1), while the opposite expression pattern is observed for DNMT1." (PMID 36382559, 2022). "The aim of the present study was to extract BSO from black seeds sourced from the local market of Al-Qassim, Saudi Arabia, to determine its content of TQ and to investigate its inhibitory effects on the expression of UHRF1, DNMT1 and HDAC1 and the related events in several cancer cells." (PMID 35566130, 2022).